ADAM17 (ADAM metallopeptidase domain 17)
Diseases named in the same sentence as ADAM17 in open-access papers (continued):
Sharing a sentence is not in itself a finding about the gene and the disease.
atherosclerosis (27 papers, 2015 to 2026). A disease characterized by the build-up of fatty material and calcium deposition in the arterial wall resulting in partial or complete occlusion of the arterial lumen. "For example, when ADAM17 is associated with the development of atherosclerosis, it promotes inflammatory responses and regulates cellular oxidative stress, and consequently exacerbates pathological changes." (PMID 40565017, 2025). "In several CVDs, the ADAM10- and ADAM17-mediated cleavage of adhesion molecules has been implicated in atherosclerosis and vascular remodeling." (PMID 37762417, 2023). "After Ang-II infusion, expression of tumor necrosis factor (TNF)-α-converting enzyme (TACE) increases in atherosclerosis and left ventricle, and ADAM17 polymorphism is associated with cardiovascular mortality." (PMID 37374349, 2023). "For example, quantitative trait locus mapping in mice demonstrated that increased Adam17 expression is associated with atherosclerosis resistance." (PMID 37108478, 2023). "The TACE expression is increased in atherosclerosis and in the left ventricle after Ang-II infusion and that ADAM17 polymorphism is associated with cardiovascular mortality." (PMID 36310604, 2022). "ADAM17 upregulation is associated with a number of chronic inflammatory diseases, including arthritis and atherosclerosis, and malignancies." (PMID 33579029, 2021). "However, they are in sharp contrast to the significantly reduced atherosclerosis development in mice with endothelial deficiency of Adam17, a family member with a large overlap in substrate repertoire." (PMID 36776254, 2023). "Interestingly, these effects are also completely opposite to the observed effects on atherosclerosis formation by endothelial Adam17-deficiency." (PMID 37108478, 2023). "ADAM17 expression has indeed been associated with atherosclerosis development." (PMID 37108478, 2023). "A disintegrin and metalloproteinase 17 (ADAM17), a type I transmembrane metalloproteinase, mediates the shedding of several transmembrane proteins in the extracellular domain and is associated with various diseases, such as atherosclerosis, adipose tissue metabolism, insulin resistance and diabetes." (PMID 37426678, 2023). "In addition, it was observed that unsaturated fatty acids in LDL particles are also involved in ADAM17 activation in the endothelial layer, due to increase in membrane fluidity, creating a link between endothelial dysfunction/atherosclerosis and increase in ADAM17 substrates in patients at risk." (PMID 27803674, 2016). "Our results align with prior studies on ADAM17, which also cleaves MerTK in lung injury and atherosclerosis models, highlighting conserved proteolytic mechanisms within the ADAM family." (PMID 41169382, 2025). "In particular, ADAM10 and ADAM17 have been extensively studied and are confirmed to be closely related to cardiovascular diseases such as atherosclerosis." (PMID 41169382, 2025). "While prior studies have shown that ADAM17 can also cleave MerTK in ventilator-induced lung injury and atherosclerosis models, our findings underscore the distinct and context-specific function of ADAM8 in SICM pathogenesis." (PMID 41169382, 2025). "This study evaluated in vivo for the first time the effects of white tea on ADAM10 and ADAM17 enzyme activities, which play an important role in the pathophysiology of atherosclerosis." (PMID 39770544, 2024).
atherosclerosis (continued). "The membrane-bound chemokines CXCL16 and CX3CL1 are not only shed by ADAM10/ADAM17 in the kidney but also play an important role in the context of atherosclerosis." (PMID 37108478, 2023). "In the case of the vascular wall, several cytokines, receptors, adhesion molecules or growth factors expressed in this tissue, and directly related to the setting of atherosclerosis, are substrates of ADAM17." (PMID 37274332, 2023). "Because these effects were alleviated with the knockdown of Tnfr2, it was confirmed that TNF-TNFR2 signaling is a crucial mechanism behind the observed ADAM17-mediated effects on atherosclerosis." (PMID 37108478, 2023). "Our results also confirmed that p38 MAPK regulated ADAM17‐mediated exo‐domain shedding in a cellular model of atherosclerosis." (PMID 37426678, 2023). "Consequently, several cellular functions are also disturbed upon Adam17-deficiency, such as increased proliferation and reduced apoptosis in macrophages and SMCs and an increased adhesion of macrophages to ECs in vitro, which are all atherosclerosis-promoting effects." (PMID 37108478, 2023). "Hypoxia has been shown to activate p38 MAPK to enhance ADAM17 expression and activity, inducing keratinocyte migration, while angiotensin II activated the p38 MAPK/ADAM17 pathway to promote Mer tyrosine kinase cleavage, facilitating atherosclerosis." (PMID 37426678, 2023). "ADAM10 and ADAM17 shed partly overlapping substrates, although they appear to have opposite functions in atherosclerosis." (PMID 37108478, 2023). "This study showed that ADAM17 has an atheroprotective role in atherosclerosis development as Adam17 hypomorphic mice have atherosclerotic lesions that are 1.5-fold larger compared to controls." (PMID 37108478, 2023). "The notion that myeloid and endothelial ADAM17 have opposing effects on atherosclerosis formation is also of crucial importance for potential future therapeutic options to target ADAM17." (PMID 37108478, 2023). "TACE, also called ADAM17, has been found to play an important role in the pathogenesis of inflammatory releases and atherosclerosis." (PMID 26655882, 2015). "Considering that in atherosclerosis ADAM17 is overactive, IL-6 is expected to present a proinflammatory role in this disease." (PMID 26578976, 2015). "ADAM17 (a disintegrin and metalloprotease 17) is responsible for cleavage of MerTK, resulting in defective efferocytosis that contributes to accumulation of apoptotic cells and tissue injury in cardiovascular diseases including atherosclerosis." (PMID 38341954, 2024). "Based on the important role of ADAM10 and ADAM17 in inflammation and the related leukocyte recruitment studied mainly in in vitro settings, it is highly likely that these ADAMs also play a crucial role in atherosclerosis formation in vivo." (PMID 37108478, 2023). "Besides a crucial role in CKD, ADAM10 and ADAM17 have been more elaborately studied in the context of CVD, particularly in atherosclerosis, the main underlying cause of CVD." (PMID 37108478, 2023). "Using the Cre-flox system, cell-specific effects of ADAM17 in atherosclerosis could be distinguished." (PMID 37108478, 2023). "In addition, ADAM17 appears to be involved in several inflammatory diseases related to the cardiovascular system, such as atherosclerosis, ischemia and heart failure." (PMID 36286024, 2022). "Selective inhibition of ADAM17 could be beneficial for the treatment of diseases implied in pathological neovascularization, such as atherosclerosis." (PMID 27803674, 2016). "In addition, targeting ADAM17 by pharmacologic inhibition or gene knockout attenuates the inflammatory response in animal models of vascular damage, including hypertension, atherosclerosis, and pulmonary vascular inflammation." (PMID 26064952, 2015).
atherosclerosis (continued). "Therefore, whether we can also prepare a TIMD4 antibody to protect it from being cleaved by ADAM17 and promote the efferocytosis of macrophages to alleviate atherosclerosis, which will be our future research direction." (PMID 37426678, 2023). "On the other hand, due to the structural and functional heterogeneity of ADAM17 substrates, the sheddase is also involved in various pathological processes such as cancer, inflammatory diseases, neurological diseases, cardiac failure, atherosclerosis, diabetes, cardiac hypertrophy, and hypertension." (PMID 27803674, 2016). "When considering CVD based on atherosclerosis, various key mediators have already been identified as substrates for ADAM10 and/or ADAM17." (PMID 36286024, 2022). "Conversely, by targeting the ADAM17/TNF axis, overexpression of TIMP-3 in mouse macrophages reduced adipose inflammation, insulin resistance and nonalcoholic fatty liver disease, other than reducing atherosclerotic plaques in a mouse model of atherosclerosis." (PMID 33579029, 2021). "However, ADAM17’s intracellular function and role in an in vivo environment are not well explored in atherosclerosis, and the atherosclerotic action of ADAM17 is not clearly understood yet." (PMID 40565017, 2025). "Upon mTNF cleavage by the TNF-alpha-converting enzyme (TACE) or ADAM17 (a disintegrin and metalloproteinase 17), the soluble (sTNF) form of mTNF can be released with higher affinity for TNFR1 and indirectly balance TNFR2 signaling, as shown in the control of atherosclerosis." (PMID 37465675, 2023). "ADAM17 is expressed in atherosclerosis-prone sites, however it is not clear whether this expression is due to an up-regulation of enzyme expression or due to its expression by newly infiltrated vascular smooth muscle cells (VSMCs) and leukocytes." (PMID 27803674, 2016). "So far, many studies in other diseases, e.g., cancer, have focused on the general inhibition of ADAM17, which at least in the context of atherosclerosis would probably not be effective due to the contradicting cell-specific effects and may even lead to unwanted side-effects." (PMID 37108478, 2023). "ADAM17 expression was unchanged between ADAM8 wildtype and knockout mice in both atherosclerosis models, suggesting there is no overcompensation for the loss of ADAM8 deficiency although this does not rule out any functional compensation." (PMID 28916789, 2017).
gastric cancer (26 papers, 2013 to 2025). A primary or metastatic malignant neoplasm involving the stomach. "Strong expression of ADAM17 was found associated to poor prognosis or aggressive disease progression in gastric cancer, hilar cholangiocarcinoma, cervical, esophageal, non-small-cell lung cancers and in high-grade breast tumors." (PMID 36140519, 2022). "Expression of IDO1, CD155, and ADAM17 is also associated with poor survival, including gastric cancer (GC)." (PMID 34943606, 2021). "In this study, we investigated the relationship between ADAM17 and prognostic value and clinicopathological parameters and found that high expression of ADAM17 was associated with poor prognoses in stomach cancer patients." (PMID 32610677, 2020). "The association between ADAM17 and gastric cancer has been described in several studies, but the significance of ADAM17 for the prognosis of the cases is inconsistent among reports." (PMID 32610677, 2020). "Moreover, high levels of ADAM17 expression can cause gastric cancer progression through the Notch and/or Wnt signaling pathway and also through the epidermal-like growth factor (EGF) pathway." (PMID 36286024, 2022). "ADAM17 is probably associated with aggressive metastasis and poor prognosis of gastric cancer." (PMID 36466812, 2022). "A meta-analysis associated with gastric cancer indicated that ADAM17 might be a tumor marker for poor prognosis in gastric cancer, and high expression of ADAM17 is associated with lymph node metastasis and clinical staging of lymph node metastasis in gastric cancer." (PMID 36466812, 2022). "Furthermore, the inhibition of TNF via ADAM17 alleviates cytokine-mediated inflammation, reduces the risk of gastric cancer and may also prevent hypochlorhydria." (PMID 31636639, 2019). "There are other ways in which ADAM10 and ADAM17 participate in gastric cancer development via various signaling pathways." (PMID 39755747, 2025). "In the current study, we identified ADAM10, ADAM12 and ADAM17 simultaneously as potential biomarkers for gastric cancer diagnosis." (PMID 39755747, 2025). "In a study of 374 patients with gastric cancer, ADAM17 expression was significantly upregulated at both, the transcriptional and translational levels in gastric cancer tissue, but did not significantly correlate with patient survival." (PMID 36572816, 2023). "The ADAM10 and ADAM17 proteins seem to play a particularly significant role in the pathogenesis of gastric cancer." (PMID 37185715, 2023). "Several analyses have investigated the relationship between ADAM17 expression and the prognosis of patients with gastric cancer." (PMID 36572816, 2023). "P65, an anti-apoptosis regulator, one of the molecules downstream TNFα, was reduced once ADAM17 downregulated, suggesting that ADAM17 promoted the development of gastric cancer through the regulation of TNFα signaling pathway." (PMID 34182543, 2021). "Decreased cell membrane receptor-bound TNFα was detected in gastric cancer cells transfected with ADAM17-shRNA." (PMID 34182543, 2021). "A report revealed that the proliferation and migration ability of the cells decreased after inhibiting the expression of ADAM17 and led to the apoptosis of stomach cancer cells." (PMID 32610677, 2020). "The progression of gastric cancer correlates with the expression of ADAM10 and ADAM17 and high ADAM10/ADAM17 expression levels were associated with patient’s poor prognosis and the establishment of lymph node metastasis." (PMID 32698506, 2020). "ADAM17 has been reported to be highly expressed in H. pylori-infected patients and in patients with gastric carcinomas." (PMID 31636639, 2019). "miR338-3p inhibits proliferation, migration and invasion of gastric cancer cells by decreasing ADAM17." (PMID 28881855, 2017). "A recent study has shown that TGFβ induces HBEGF shedding and EGFR transactivation through ADAM17 activation in gastric cancer cells." (PMID 27802351, 2016).
gastric cancer (continued). "Furthermore, ADAM17 facilitates EMT in gastric cancer cells by activating the TGF-β/Smad signaling pathway, thereby contributing to tumor progression and metastasis." (PMID 40143211, 2025). "Micro RNAs are also involved in gastric cancer development by influencing ADAM10 or ADAM17." (PMID 39755747, 2025). "A meta-analysis revealed ADAM17 as a significant biomarker for poor prognosis in gastric cancer." (PMID 35269560, 2022). "It was reported that ADAM17 promotes EMT in gastric cancer cells." (PMID 36466812, 2022). "ADAM17 promotes gastric cancer cell metastasis by activating the Notch-Wnt signaling pathway." (PMID 36466812, 2022). "Besides, a recent study showed that ADAM17 knockdown inhibited the expression of TGF-β in gastric carcinoma cells, with the downstream Smad2 and Smad3 also being attenuated." (PMID 36313337, 2022). "Hence, this is a confirmation that ADAM17 promotes EMT probably via TGF-β/Smad signalling in gastric carcinoma." (PMID 34362154, 2021). "In conclusion, ADAM17 promotes proliferation, migration and invasion in gastric carcinoma cells." (PMID 34362154, 2021). "ADAM17 may be an important biomarker for prognosis of gastric cancer patients and play an important role in the development and progression of gastric cancer." (PMID 32610677, 2020). "In addition, ADAM17 can promote epithelial mesenchymal transition and proved that it is a therapeutic target for stomach cancer." (PMID 32610677, 2020). "The proliferation and invasion of stomach cancer cells were decreased when the ADAM17 was knockdown from these cells, and the ability of proliferation and invasion was significantly enhanced after these cancer cells were transfected with ADAM17-shRNA." (PMID 32610677, 2020). "Helicobacter pylori infection may increase the incidence of gastric cancer and can increase the expression of ADAM17 in AGS gastric epithelial cells." (PMID 32610677, 2020). "ADAM17 is a significant biomarker for poor prognosis in gastric cancer." (PMID 32610677, 2020). "Hence, progression of gastric cancer is not only promoted by ADAM17 on tumour cells, but also on cells of the tumour micro-environment." (PMID 32698506, 2020). "Further, expression of ADAM17 has been found to be markedly upregulated in gastric cancer." (PMID 28881855, 2017). "The mechanism of ADAM17 in gastric cancer may be through TGF-β/p-Smad2/3-mediated EMT activation." (PMID 36466812, 2022). "Compared to ADAM10 and ADAM17, the role of ADAM12 in relation to gastric cancer development is relatively less studied." (PMID 39755747, 2025). "That is, ADAM17 mediated MUC1 shedding induced by H. pylori infection may have caused increased expression of MUC1 as a coping mechanism although it failed to prevent gastric cancer development." (PMID 39755747, 2025). "Gastric cancer tissues (n = 415) expressed significantly higher mRNA levels of ADAM8, ADAM9, ADAM10, ADAM12, and ADAM17 (p < 0.001) than normal tissues (n = 35)." (PMID 39755747, 2025). "Above studies support that ADAM12, ADAM17 and ADAM10 hold potential as biomarkers for gastric cancer." (PMID 39755747, 2025). "When gastric cancer tissue was paired with normal tissue from the same patient with gastric cancer (n = 32), ADAM8, ADAM9, ADAM10, ADAM12, and ADAM17 mRNAs showed significantly higher expression in gastric cancer tissues (p < 0.05)." (PMID 39755747, 2025). "We believe that ADAM12, ADAM17 mRNA and ADAM10 protein are worth further investigation as biomarkers for gastric cancer screening, and that players in the ADAM-NKG2D axis are worth investigation for cancer diagnostics and therapeutics." (PMID 39755747, 2025). "In gastric cancer cell lines, EMT was critically dependent on ADAM17, and knockdown of ADAM17 was able to reverse EMT transition by abrogating signaling via the TGF-β/Smad axis." (PMID 35269560, 2022).